UHRF1 (ubiquitin like with PHD and ring finger domains 1)
Diseases named in the same sentence as UHRF1 in open-access papers (continued):
Sharing a sentence is not in itself a finding about the gene and the disease.
cancer (continued). "As in many other cancer cells, human RB cell lines including Y79 and Weri‐Rb1 display high expression of UHRF1, at least partially by E2F‐mediated transcriptional upregulation." (PMID 32840881, 2021). "In cancer cells, UHRF1 is frequently overexpressed constitutively and known to promote tumor development by introducing changes in DNA and histone modifications via recruitment of various chromatin modifiers and thereby altering gene expression." (PMID 32840881, 2021). "Given the well‐known role of UHRF1 in regulation of DNA methylation in both normal and cancer cells, functions of UHRF1 in the establishment and maintenance of RB methylomes were investigated using UHRF1‐knockdown Y79 cells and two murine RB models." (PMID 32840881, 2021). "Uhrf1 is an epigenetic modifier with multiple fields and functions and is overexpressed in many cancers." (PMID 33744855, 2021). "The increasing role of the UHRF1/DNMT1/HDAC1/G9a complex in the epigenetic silencing of many TSGs in cancer supports the targeting of this multiprotein complex as a valuable approach for developing multitarget single epidrugs." (PMID 33922029, 2021). "UHRF1 is involved in various cellular processes that lead to tumorigenesis and thus attracted considerable attention as a potential anti-cancer drug target." (PMID 32448288, 2020). "In vitro and in vivo studies have shown that a drug-induced inhibition of UHRF1 activity or expression leads to the reactivation of tumor suppressor genes, enabling cancer cells to undergo apoptosis and cell cycle arrest." (PMID 32213189, 2020). "UHRF1 is highly expressed in cancer cells, and it is thought that its level is correlated with the ability of cancer cells to proliferate." (PMID 33177984, 2020). "Ubiquitin-like with PHD and RING finger domain 1 (UHRF1) is a critical molecule that participates in regulating DNA methylation and is usually overexpressed in many cancers, including HCC." (PMID 32593303, 2020). "Normalization of DNMTs and UHRF1 to other markers of cancer cell proliferation, including PLK1 and BUB1, provided similar results as seen with MKI67 normalization." (PMID 32213861, 2020). "The chromatin-binding E3 ubiquitin ligase ubiquitin-like with PHD and RING finger domains 1 (UHRF1) contributes to the maintenance of aberrant DNA methylation patterning in cancer cells through multivalent histone and DNA recognition." (PMID 33097091, 2020). "According to previous studies about how UHRF1 affects the progression of cancer, we made two conclusions on the molecular mechanisms: Firstly, UHRF1 plays an important role in transferring DNA methylation status from mother cells to daughter cells." (PMID 32495469, 2020). "In primary cultured human lung fibroblasts, UHRF1 expression peaked at late G1 and during the G2/M phase; conversely, in cancer cell lines such as HeLa, Jurkat, and A549, constant UHRF1 expression is observed throughout the entire cell cycle." (PMID 34766114, 2020). "Knockdown of UHRF1 expression in cancer cells significantly suppressed cell growth, indicating that UHRF1 is essential for the progression of cancer." (PMID 32213189, 2020). "In view of these results, we postulate that UHRF1 is essential for proliferation in human cancer cell." (PMID 32495469, 2020). "We found UHRF1 was up‐regulated in multiple cancers compared with normal controls from ONCOMINE data and obtained the similar results from TIMER data derived from TCGA clinical patients." (PMID 32495469, 2020). "Ubiquitin-like with PHD and RING Finger domains 1 (UHRF1), a potential target of BBR, is highly expressed in various cancer cells, and its overexpression has been associated with tumor-promoting effects." (PMID 32213189, 2020). "Given the profound effect of 2i culture condition on mESCs pluripotency, DNA methylation and UHRF1/DNMT1 expression, here we investigated if and how 2i regulates UHRF1/DNMT1 expression in cancer cells." (PMID 30696879, 2019).
cancer (continued). "Numerous studies have proven that UHRF1 expression is up-regulated in a variety of cancer cells, which drives the malignant growth." (PMID 30710064, 2019). "In the present study, we showed that UHRF1 depletion rapidly induces genome-wide DNA demethylation in cancer cells." (PMID 31064417, 2019). "As the MEK/ERK pathway is widely activated, as a result of RAS or BRAF mutations and others, in human cancer cells, our finding provides a reasonable explanation for widespread transcriptional overexpression of UHRF1 (DNMT1 as well) in various cancers." (PMID 30696879, 2019). "In this study, we observed that RP11-424C20.2 expression was strongly correlated with its parental gene UHRF1 expression in 8 types of human cancer." (PMID 31442209, 2019). "Since UHRF1 is overexpressed in almost all major types of cancer, its role as a universal biomarker for cancer has also been proposed." (PMID 31245293, 2019). "Taken together, these data indicated that 2i can broadly but not universally suppress the transcription of DNMT1 and especially UHRF1 in various cancer cell lines." (PMID 30696879, 2019). "In general, UHRF1 can be a potential cancer drug target, whose overexpression correlates with aggressiveness of multiple human malignancies." (PMID 30710064, 2019). "Knockdown or silencing of UHRF1 in cancer cells leads to reduced proliferation and increased apoptosis." (PMID 30710064, 2019). "Aberrant expression of UHRF1 was related to aggressiveness of multiple human malignancies, where knockdown of UHRF1 led to decreased proliferation of cancer cells." (PMID 30710064, 2019). "Aberrant expression of UHRF1 was related to aggressiveness of multiple human malignancies, whereas knockdown or silencing of UHRF1 in cancer cells led to decreased proliferation and increased apoptosis." (PMID 30710064, 2019). "UHRF1 is overexpressed in a number of cancer types, and its depletion has been shown to inhibit growth and invasion of cancer cells." (PMID 31105884, 2019). "Quantitative RT-PCR analysis revealed that 2i treatment induced a variable but significant reduction of UHRF1 transcripts in all above cancer cells with the exception of KYSE510." (PMID 30696879, 2019). "To assess the expression of UHRF1 in cancer, we first used RNA-seq data obtained from primary CRC and normal colonic tissues in The Cancer Genome Atlas (TCGA) study." (PMID 31064417, 2019). "Aberrant UHRF1 expression in cancer cells has been reported to be regulated transcriptionally by transcription factors such as E2F123,24, E2F825, SP126 and FOXM127, and post-transcriptionally by micro RNAs28–33." (PMID 30696879, 2019). "Ubiquitin-like with PHD and RING Finger domains 1 (UHRF1) is helpful in repairing damaged DNA as it increases the resistance of cancer cells against cytocidal drugs." (PMID 31428652, 2019). "Accumulative studies demonstrate that UHRF1 is broadly overexpressed in cancers, which contributes to cancer cell proliferation and tumorigenesis." (PMID 30696879, 2019). "To further explore potential function of RP11-424C20.2 in the cancer development, we performed gene ontology (GO) and Kyoto Encyclopedia of Genes and Genomes (KEGG) pathway enrichment analysis of the top 200 correlated genes of UHRF1 in the 8 types of cancer." (PMID 31442209, 2019). "In fact, multiple studies have identified UHRF1 overexpression as a powerful marker for cancer diagnosis and prognosis." (PMID 30696879, 2019). "It is also possible that UHRF1 has similarly complex actions in cancer cells, and further study is warranted." (PMID 31064417, 2019). "This suggests UHRF1 is essential for maintaining DNA methylation in cancer cells and is generally more involved in the hypermethylation of tumor-related genes than the previously documented." (PMID 31064417, 2019). "The UHRF1 gene is an epigenetic modification factor that mediates tumor suppressor gene silencing in a variety of cancers." (PMID 31803739, 2019).
cancer (continued). "We further demonstrated that it is the MEK/ERK pathway that controls a coordinated transcription of UHRF1/DNMT1 in cancer cells." (PMID 30696879, 2019). "Pearson correlation analysis revealed a strong positive relationship between RP11-424C20.2 and UHRF1 in all 8 types of cancer." (PMID 31442209, 2019). "For global DNA hypomethylation, a diminished interaction was suggested between UHRF1 and DNMT1, although UHRF1 expression is enhanced in all cancers so far investigated." (PMID 30669400, 2019). "Here we present evidence that while addition of 2i broadly downregulates UHRF1 and DNMT1 in various cancer cells, distinct underlying mechanisms are involved." (PMID 30696879, 2019). "So far we have demonstrated that 2i has a broad effect on UHRF1 and DNMT1 expression in cancer cells and that the effect of 2i on UHRF1 and DNMT1 expression is due to specific inhibition of MEK/ERK pathway." (PMID 30696879, 2019). "Ectopic expression of UHRF1 promotes cancer cell proliferation, while UHRF1 knockdown induces cell cycle arrest, DNA damage response, and apoptosis in cancer cells." (PMID 31064417, 2019). "UHRF1, a potent oncogene overexpressed in many human cancer cells, plays an important role in G1/S transition and the epigenetic silencing of various TSGs such as p16INK4A, p14ARF, BRCA1 and RB1." (PMID 29983883, 2018). "In fact, UHRF1 is so widely overexpressed in solid tumors that it has been suggested as a universal biomarker for cancer." (PMID 29507645, 2018). "ATC and many other cancers, of which UHRF1 were highly expressed, have the strong ability of proliferation, invasion and metastasis." (PMID 30174788, 2018). "Accordingly, it has recently been shown that UHRF1 down-regulation in cancer cells induced caspase-8 dependent apoptosis and the activation of caspase-3." (PMID 29983883, 2018). "Ubiquitin-like with PHD and ring-finger protein 1 (UHRF1) has a key role in several kinds of cancers development." (PMID 30352833, 2018). "We verified the suppression effects of UHRF1 in cancer cells by real-time RT-PCR and western blot assay." (PMID 30174788, 2018). "Imbalance of UHRF1 levels in cells plays a significant role in cancer initiation, metastasis, and tumor relapse." (PMID 29899856, 2018). "UHRF1 has been recognized recently as a major molecular marker of human cancers, of which the overexpression is related to the poor prognosis." (PMID 30174788, 2018). "UHRF1 is a nuclear protein which plays an important role in the development of cancer by epigenetic regulation." (PMID 29786770, 2018). "Elevated transcription of UHRF1 mRNA was correlated with an advanced cancer stage, poor histological differentiation, and poor prognosis." (PMID 29899856, 2018). "The overexpressed UHRF1 in cancer cells led to an increased expression of oncogene (topoisomerase IIα) and decreased expression of tumor suppressor genes (RB1, p16INK4A and p14ARF)." (PMID 30174788, 2018). "FOXM1 and UHRF1 were overexpressed in the taxane-resistant cancer cells, and positively regulated the maintenance of CSCs." (PMID 29752436, 2018). "Our study also provides new insights into the regulation of UHRF1 expression upon treatment with natural anti-cancer drugs." (PMID 29983883, 2018). "The pro-oncogenic role of UHRF1 is causally related to its role in establishment of DNA methylation; indeed, overexpression of UHRF1 facilitates coordinated tumor suppressor gene silencing in multiple cancers by altering DNA methylation patterns." (PMID 29899856, 2018). "Several studies showed that UHRF1 is recruited to DNA damage sites and required for DNA damage recognition in response to irradiation and DNA interstrand crosslinks in various cancer cells." (PMID 29415984, 2018). "UHRF1 has been gaining attention in cancer research not only as an important epigenetic regulator for DNA methylation and histone modifications but also as a critical regulator for cancer cell proliferation and survival." (PMID 29415984, 2018).
cancer (continued). "In this study, UHRF1 overexpression was detected in taxane-resistant cancer cells, and the depletion of UHRF1 correspondingly lowered the expression of CSC-associated molecules and decreased the subpopulation of CSCs and sphere formation ability." (PMID 29752436, 2018). "Consistently in three pairs of cell lines, UHRF1 protein levels were significantly higher in docetaxel-resistant cells than the parental cancer cells." (PMID 29752436, 2018). "In summary, the SRA domain of UHRF1 is emerging as an attractive target to treat cancers characterized by UHRF1 overexpression and DNA hypermethylation." (PMID 29899856, 2018). "Consistent with these earlier findings, overexpression or downregulation of UHRF1 in various cancer cell lines decreased or increased the radiosensitivity." (PMID 29415984, 2018). "Consistently in the DU145-DR and CNE2TR docetaxel-resistant cancer cells, protein levels of CSC-associated molecules declined with UHRF1 knockdown." (PMID 29752436, 2018). "Strikingly, in two cancer cells tested, suppression of UHRF1 successfully inhibited the cell proliferation ability as judged by colony formation." (PMID 30174788, 2018). "UHRF1 depletion consistently and significantly decreased sphere formation by the two taxane-resistant cancer cell lines compared to the parental cancer cells." (PMID 29752436, 2018). "E2F transcription factor 1 (E2F1) and E2F transcription factor 8 (E2F8) are upregulated in many cancers and stimulate UHRF1 expression by directly binding to different sites in its promoter region." (PMID 28881702, 2017). "UHRF1 overexpression was found in 78.3% (47/60) of cancer tissue samples, whereas remaining 13 samples had relatively lower expression of UHRF1 and in normal tissues, UHRF1 expression was barely detectable." (PMID 28881702, 2017). "UHRF1 overexpression also correlated with the histological and pathological stages of cancer and was found in undifferentiated cells in advanced stages of cancer." (PMID 28881702, 2017). "Significantly higher levels of UHRF1 were detectable in specimens with non-invasive or superficially invasive cancers at very early stages compared to normal cells." (PMID 28881702, 2017). "Some authors consider UHRF1 gene as an oncogene which overexpression leads to hypomethylation phenomenon in cancer genomes." (PMID 28128913, 2017). "It is also employed to predict the prognosis of cancer as high level of UHRF1 is generally correlated to poor survival rate, resistance to therapy and recurrence of malignancy." (PMID 28881702, 2017). "Latter, it was described that UHRF1 gene expression is only detectable in proliferating cells, not in quiescent cells and that this gene is overexpressed in numerous malignant neoplasms including lung, breast, prostate, pancreatic and cervical cancer." (PMID 28128913, 2017). "An increasing body of evidence suggests that UHRF1 is an oncogene, demonstrated by its tumor-promoting functions in proliferation, invasion, and regulation of apoptosis in various cancer cells." (PMID 28467809, 2017). "In cancer cells, UHRF1 is overexpressed and promotes the proliferation and dedifferentiation of cells." (PMID 28881702, 2017). "Although the basal level of UHRF1 in these cancer cells was higher than that in HFHs, it was greatly reduced in Huh7 cells compared with the other cancer cells." (PMID 28584306, 2017).
cancer (continued). "Another cohort study of 160 ESCC patients demonstrated that UHRF1 is as an attractive prognostic marker and potential target for cancer therapy as high levels of UHRF1 corresponded to poor survival rate." (PMID 28881702, 2017). "Previously, we found that the downregulation of UHRF1 leads to the induction of EMT via CXCR4 in human cancer cells." (PMID 28584306, 2017). "UHRF1 is up-regulated in multiple types of cancers (breast, lung, colorectal, prostate, bladder, liver), promoting cell proliferation and TSG promoter methylation, and inhibiting apoptosis." (PMID 28587163, 2017). "UHRF1 is a key mediator of inheritance of epigenetic DNA methylation patterns during cell division and is a putative target for cancer therapy." (PMID 29074623, 2017). "Involved in tumourigenesis and cancer progression, UHRF1 is suspected of being a hepatocellular oncogene due to its overexpression having the ability to destabilize and delocalize DNMT1." (PMID 28587163, 2017). "In human cancers, UHRF1 is frequently overexpressed and cancer genomes often exhibit a diverse level of global DNA hypomethylation as compared with their normal tissues." (PMID 28467809, 2017). "Pharmacological inhibition of heat shock protein (HSP90) also destabilizes UHRF1 and suppress cancer cell proliferation predicting a role of HSP90 in UHRF1 turnover." (PMID 28881702, 2017). "In cancer cells, UHRF1 is mostly up-regulated and its levels are maintained constant throughout the cell cycle." (PMID 29268763, 2017). "Altogether these events result in abnormal high level of UHRF1 in cancers which appears now to be exploitable as a biomarker." (PMID 28881702, 2017). "UHRF1 is a potential therapeutic target, because it is essential for the maintenance of DNA methylation patterns and highly expressed in most cancers." (PMID 29074623, 2017). "Immunohistochemistry staining of 106 gastric tumors revealed higher expression of UHRF1 in cancer tissues compared with adjacent normal tissues, which correlated with poor differentiation, cancer staging, increased lymph node and tissue metastasis." (PMID 28881702, 2017). "Researchers have recently shown that the proliferative ability of cancer cells was inhibited after UHRF1 knockdown." (PMID 28060737, 2017). "The overexpression of UHRF1 gene was recently described in many cancers, including urinary bladder TCC." (PMID 28128913, 2017). "UHRF1 on the other hand, is known to play an oncogenic role in cancer as its high expression in cancer is often related to downregulation of tumor suppressor genes through promoter hypermethylation." (PMID 29268763, 2017). "UHRF1 overexpression has also proven to be a barrier to cure cancer because of its ability to silence tumor suppressor genes depending on the cancer type or to counteract pro-apoptotic genes and to induce therapy resistance." (PMID 28881702, 2017). "It is remarkable to notice that a paradigm is emerging concerning the decreased sensitivity of cancer cells to chemotherapy through control of the DNA repair machinery by UHRF1." (PMID 28881702, 2017). "The expression of UHRF1 in non-cancer cells is regulated along the cell cycle which culminates at late G1 phase and is required for the S phase entry in some cell types." (PMID 28467809, 2017). "Here in this review we analyze the potential of Ubiquitin-like containing PHD and Ring Finger domain 1 (UHRF1) as a universal biomarker for cancers." (PMID 28881702, 2017). "The high levels of UHRF1 found in variety of cancers are often correlated to the epigenetically silencing of tumor suppressor genes, poor prognosis and aggressiveness of the tumor." (PMID 29268763, 2017). "It is therefore essential to target UHRF1 overexpression to achieve therapeutic goals in cancer patients." (PMID 28881702, 2017). "We will now review the potential of UHRF1 to fulfil the features of a biomarker in various types of cancer." (PMID 28881702, 2017).